SHISAL2B (shisa like 2B)
Synonyms: FAM159B
Tractability: Antibody: UniProt predicts a signal peptide or a membrane-spanning region.
Gene: Protein-coding gene on chromosome 5 (64,690,442 to 64,718,190, forward strand). Ensembl gene ENSG00000145642.
Subcellular location: Membrane
Gene Ontology:
Cellular component: membrane
Genetic constraint (gnomAD): Loss-of-function variants: 13 observed, 14.79 expected, observed/expected ratio (o/e) 0.88, 90% interval 0.57 to 1.4. The upper end of that interval is the gene's LOEUF score, 1.4, which puts it in group 5 of 6, group 1 being the genes least tolerant of losing a copy. Missense variants: 183 observed, 175.36 expected, observed/expected ratio (o/e) 1.04, 90% interval 0.92 to 1.18. Synonymous variants: 72 observed, 71.71 expected, observed/expected ratio (o/e) 1, 90% interval 0.83 to 1.22.
Homologues: Orthologues: chimpanzee SHISAL2B (100% identical), macaque SHISAL2B (98% identical), pig SHISAL2B (89% identical), rat Shisal2b (87% identical), guinea pig SHISAL2B (84% identical), mouse Shisal2b (84% identical), rabbit SHISAL2B (84% identical), dog SHISAL2B (81% identical), tropical clawed frog shisal2b (57% identical). Paralogues in human: SHISAL2A (44% identical), SHISA2 (19% identical), SHISA3 (18% identical), SHISA4 (18% identical), SHISAL1 (17% identical).
Diseases named in the same sentence as SHISAL2B in open-access papers:
SHISAL2B is named in the same sentence as 22 diseases in open-access papers, as found by Europe PMC text mining. Sharing a sentence is not in itself a finding about the gene and the disease. The quoted sentences say what the papers report.
arthrogryposis (1 paper, 2022). A rare, non-progressive congenital disorder characterized by multiple joint contractures which are present at birth. "However, in the Angus cattle, although there were genes involved in inflammatory disease (OXT) and microcystic adenoma (SHISAL2B), the main function of DEGs was enriched in arthrogryposis (TNNT3 and TNNI2) and myopathy and myasthenic syndrome (MSTN, MYH2, and SLN)." (PMID 35495650, 2022).
sarcopenia (1 paper, 2025). Progressive decline in muscle mass due to aging which results in decreased functional capacity of muscles. "Genes with inconsistent directions, Per1, Shisal2b, AW551984, and those located in the second and fourth quadrants of the LogFC vs. correlation plot, were considered less likely to be directly involved in sarcopenia." (PMID 40869189, 2025).
SHISAL2B also shares sentences with these, for which no sentence is quoted: cancer (2 papers); neuroendocrine neoplasm (2); tumour (2); adenocarcinomas of the lung (1); anaplastic thyroid carcinomas (1); breast carcinoma (1); cervical cancer (1); colon carcinoma (1); gastric adenocarcinoma (1); lymph node metastases (1); lymphoma (1); melanoma (1); myopathy (1); ovarian carcinoma (1); pancreatic adenocarcinoma (1); papillary thyroid carcinomas (1); parathyroid adenomas (1); pituitary adenomas (1); prostate carcinoma (1); squamous cell carcinomas of the lung (1).